NPY4R2 (neuropeptide Y receptor Y4-2)
Description:
G protein-coupled receptor for PPY/pancreatic polypeptide/PP, NPY/neuropeptide Y and PYY/peptide YY that is negatively coupled to cAMP. The rank order of affinity for these polypeptides and their derivatives is PP, PP (2-36) and [Ile-31, Gln-34] PP > [Pro-34] PYY > PYY and [Leu-31, Pro-34] NPY > NPY > PYY (3-36) and NPY (2-36) > PP (13-36) > PP (31-36) > NPY free acid.
Synonyms: CH17-360D5.1; PP1; PPYR1
Tractability: Antibody: UniProt places it where antibodies can reach, with medium confidence; UniProt predicts a signal peptide or a membrane-spanning region; its Gene Ontology location is reachable by antibodies, with medium confidence.
Gene: Protein-coding gene on chromosome 10 (47,918,662 to 47,925,736, forward strand). Ensembl gene ENSG00000264717.
Subcellular location: Cell membrane
Gene Ontology:
Molecular function: pancreatic polypeptide receptor activity; peptide YY receptor activity; G protein-coupled receptor activity; neuropeptide Y receptor activity
Biological process: neuropeptide signaling pathway; G protein-coupled receptor signaling pathway
Cellular component: neuron projection; plasma membrane; membrane
Genetic constraint (gnomAD): Loss-of-function variants: 0 observed, 1.72 expected, observed/expected ratio (o/e) 0, 90% interval 0 to 1.47. That is too few expected variants to judge how well the gene tolerates losing a copy. Missense variants: 1 observed, 29.87 expected, observed/expected ratio (o/e) 0.0335, 90% interval 0.011 to 0.16. Synonymous variants: 0 observed, 11.48 expected, observed/expected ratio (o/e) 0, 90% interval 0 to 0.26.
Homologues: Orthologues: chimpanzee NPY4R (99% identical), macaque NPY4R (96% identical), dog NPY4R (86% identical), guinea pig Npy4r2 (83% identical), rabbit NPY4R (82% identical), mouse Npy4r (75% identical), tropical clawed frog XB996286 (48% identical). Paralogues in human: NPY4R (99% identical), NPY1R (44% identical), PRLHR (30% identical), NPY2R (27% identical), GPR83 (26% identical), NPY5R (26% identical), TACR1 (24% identical), TACR3 (24% identical), TACR2 (23% identical), PROKR1 (22% identical), PROKR2 (22% identical), MTNR1B (20% identical), and 21 more.
Diseases named in the same sentence as NPY4R2 in open-access papers:
NPY4R2 is named in the same sentence as 2 diseases in open-access papers, as found by Europe PMC text mining. Sharing a sentence is not in itself a finding about the gene and the disease. The quoted sentences say what the papers report.
Anxiety (1 paper, 2020). Intense feelings of nervousness, tension, or panic often arise in response to interpersonal stresses. "NPY4R and NPY4R2 encode neuropeptide Y receptors; neuropeptide Y is a gut-brain peptide which modulates multiple physiologic processes, including feeding behavior and anxiety." (PMID 32780866, 2020).
NPY4R2 also shares sentences with these, for which no sentence is quoted: Esotropia (1 paper).